TNF (tumor necrosis factor)
Diseases named in the same sentence as TNF in open-access papers (continued):
Sharing a sentence is not in itself a finding about the gene and the disease.
cancer (continued). "The crosslinking of ILT7 and BST2 strongly inhibits the production of IFN-α and proinflammatory cytokines (e.g. TNF-α) by pDCs; however, the role of this interaction in cancer is still unclear." (PMID 39020402, 2024). "These immune cells, capable of secreting cytokines such as interferon-γ and tumor necrosis factor-alpha (TNF-α), contribute to better prognosis by inducing apoptosis and suppressing cancer cell proliferation, invasion, and migration." (PMID 38956686, 2024). "Two different cancer markers, including tumor necrosis factor alpha (TNF-α, 17.3 kDa) and interleukin-6 (IL-6, 20.9 kDa), were used in this targeting experiment." (PMID 38161210, 2024). "Among these pathways, “Th17 cell differentiation” and the “TNF signaling pathway” have been reported to be correlated with the proliferation, invasion, and metastasis of cancer in patients." (PMID 38233760, 2024). "Mutations in KRAS codon 12 or 13 lead to cancer cell-intrinsic production of CXCL1, a chemokine which recruits MDSC and stimulates MDSC to produce tumor necrosis factor (TNF)." (PMID 39518557, 2024). "Knowledge of how TNF-α affects cancer growth and creating individualized treatment plans requires an understanding of how it interacts with other elements in the TME." (PMID 38654309, 2024). "Since its receptors are expressed both on the surface of epithelial and stromal cells, TNF-α can modify TME to enhance cancer development." (PMID 39201656, 2024). "Some studies and publications have reported a relationship between dysregulation of expression of some cytokines, including IL-1, IL-2, IL-4, IL-6, LPC2, TNF-α, etc., and incidence of cancer, cancer invasivity, and metastases." (PMID 38541074, 2024). "Among dozens of cytokine payloads, IL2, IL12, and TNF have emerged as some of the most efficient immunomodulatory proteins in preclinical models of cancer." (PMID 38448543, 2024). "This confirms that M-DCsTNF CM kills the cancer cells through TNF in the presence of an IAP antagonist." (PMID 39105847, 2024). "10-HDA inhibited the secretion of TNF-α which promotes the proliferation of cancer cells and their malignant transformation." (PMID 38892209, 2024). "The main cause is thought to be due to increased inflammatory cytokines Interleukin-1 (IL-1), IL-6, and Tumor Necrosis Factor- (TNF-) Alpha in cancer patients." (PMID 38392941, 2024). "Cancer cells also overexpress some pro-inflammatory factors, such as IL-6 and tumor necrosis factor α (TNF-α), that can stimulate adipocyte phenotype in a paracrine fashion." (PMID 39040042, 2024). "The TNF signaling pathway is closely related to inflammation as well as cancer, and it also activates various pathways, including NFκB and MAPK." (PMID 38225547, 2024). "This enables the eradication of cancer cells, reprogramming the cellular decision balance towards inflammation and/or apoptosis by controlling TNF-α via NF-kappaB signaling." (PMID 39009887, 2024). "Cancer controls (B) receiving only AOM showed statistically the highest number of pro-inflammatory cytokines (TNF-α and IL-6) and lowest anti-inflammatory cytokines (IL-10) in their tissue homogenates." (PMID 38191592, 2024). "The elevated production of pro-inflammatory factors like tumor necrosis factor (TNF)-alpha, interleukin (IL)-6 and C-reactive protein in chronic inflammation promotes cancer development." (PMID 39272806, 2024). "To examine the effect of inflammatory cytokines, we treated the cells with HMGB1 and TNFα for 48 h at concentrations equivalent to those in the cancer ascites (50 μg/mL and 35 pg/mL, respectively) and examined the changes in 4HNE, PINK1, and Parkin." (PMID 39000167, 2024). "This EMT is also potentially subject to crosstalk with TNF-α, which enhances the EMT by causing cancer cells to switch to a cytokine- and chemokine-secreting phenotype, increasing the capacity for invasion." (PMID 38539448, 2024).
cancer (continued). "The PPM along with Quercetin as reference was used to assess the cytotoxic effect on THP-1 cells and describe its effect on pro-inflammatory cytokines such as COX-2, TNF-α, IL-6 against cancer cell line by flow cytometry." (PMID 40190537, 2024). "TNFα and IL-2 are incorporated into OAds to selectively infect cancer cells through tumor-specific promoters and knob protein exchange, thereby enhancing cancer cell entry." (PMID 39055561, 2024). "Despite the therapeutic potential of TNF-α in cancer treatment, significant obstacles remain, including toxicity, development of resistance, and inconsistent patient responses, which require further investigation and optimization." (PMID 39483536, 2024). "Following treatment with 5-azacytidine, we found that the PTX3 transcripts were restored in cancer cells but IL-1β and TNF-α exerts a different effect on the induction of PTX3 gene in a cell type-specific manner." (PMID 38243273, 2024). "The mechanism involves multiple signal pathways, through multiple pathways and targets, which are mainly related to inflammatory response, cancer pathway, and TNF signaling pathway, mediated by PI3K-Akt signaling pathway." (PMID 38875382, 2024). "-Significant reduction in cell viabilities of MCF7 and A549 cancer cell lines to 31.25% and 28.13% at the highest concentration of 100 μM, respectively.-Significant increase in TNF-α levels and apoptosis levels." (PMID 39591094, 2024). "In the IC group (n = 4), the biologics prescribed prior to cancer diagnosis included anti-TNFα in two patients (50%), anti-IL-12/23 in one patient (25%), and anti-IL-23 in the remaining patient." (PMID 38610706, 2024). "Due to its complex role as an oncogene and a potential tumor suppressor, TNF-α has gained considerable interest in contemporary cancer research." (PMID 39243014, 2024). "The results suggest that jacaranone selectively enhances the apoptotic effects induced by TNFα in cancer cells." (PMID 39769432, 2024). "Another inflammatory cytokine-TNF-α and microbe-sensing TLRs can stimulate NF-κB signaling and thus promote cancer progression and development of cancer resistance." (PMID 37789138, 2024). "In this study, an anti-TNFα nanobody was bonded to the RGD4C peptide to examine the anti-cancer activity in vitro and in vivo." (PMID 38341580, 2024). "Low doses of apigenin stimulated cancer cell growth, while high doses activated apoptosis via the TNF-α pathway." (PMID 38698424, 2024). "When the transplanted mitochondria increase ROS within cancer cells, the excess ROS stimulates the release of TNF-α, which then activates its corresponding receptors, triggering the recruitment of related proteins to the cell membrane." (PMID 38769583, 2024). "Apart from being a major mediator of cancer-related inflammation, TNFα is involved in processes including cell survival and apoptosis." (PMID 37874427, 2024). "In cancer, growth factors and cytokines (e.g., TNF‐α) were reported to be one of the ROS‐generating factors." (PMID 39629553, 2024). "Procoagulant cytokines, including interleukin (IL)-1, IL-6, and tumor necrosis factor (TNF)-a, promote the upregulation of tissue factor (TF) and cancer procoagulant (CP) expression, amplifying thrombotic risk." (PMID 39766214, 2024). "It is noteworthy that tumor necrosis factor alpha (TNF-α) has been reported to play a critical role in some cancers and SCZ development." (PMID 38592583, 2024). "Such as IFN-γ and TNF-α, both produced by NK cells and activated T cells, further enhancing the proliferation of T cells and slowing down the proliferation of cancer cells." (PMID 38622609, 2024). "There is substantial evidence that TNF-α can be involved in the promotion and progression of experimental and human cancers." (PMID 38553639, 2024).
cancer (continued). "An in vitro study showed that MNPs can enter the cells through endocytosis, causing damage to cellular microstructures and an increase in the expression of JNK1/2/3 and TNF-α, a pathway involved in cancer-related pathways." (PMID 39200683, 2024). "Further evaluation is warranted to elucidate the dose–effect relationship for the treatment suppression of IL10, TNF-α, and IL12p70 in monocytes, PMNs, and B cells under IgM stimulation as potential infections during the treatment for cancer patients." (PMID 39513832, 2024). "Both exogenous and macrophage-produced TNF accelerate the epithelial–mesenchymal transition (EMT), a mechanism that characterizes the progression of carcinoma and has been linked to the acquisition of an invasive phenotype." (PMID 39684816, 2024). "As for the TNF-α levels of stage III carcinoma patients, they were also significantly higher in relation to healthy women." (PMID 38793599, 2024). "Tumor necrosis factor-alpha has been shown to significantly elevate PGE2 synthesis and COX-2 transcription in carcinoma-associated colon fibroblasts." (PMID 39830670, 2024). "TNF antagonists are helpful if TNF-α is elevated. administering steroids with anti-cancer drugs (bortezomib, gemcitabine) avoided the recurrence of SCLS." (PMID 37261188, 2023). "Collectively, data suggested that inhibition of cancer cell growth was mediated by TNF-α produced by M1-type pro-inflammatory macrophages activated by those extract." (PMID 36802384, 2023). "Results from laboratory research about the effects of opioids on the TNF-α release and cancer cell biology are inconclusive, and further investigations are required." (PMID 36765695, 2023). "Caspase-3 can also be stimulated by tumor necrosis factor α (TNF- α) or cancer chemotherapeutic drugs to induce apoptosis." (PMID 37208730, 2023). "KEGG analysis revealed the cancer-related signaling pathways NF-kappa B pathway, TNF pathway, TGF-β pathway, and PI3K-Akt pathway and viral carcinogenesis were significantly active in basement membrane-associated lncRNAs." (PMID 37893009, 2023). "Basic research on the impact of ketamine administration on TNF-α production in cancer cell biology is limited." (PMID 36765695, 2023). "Briefly, the M1 phenotype is responsible for anti-cancer effects through the production of pro-inflammatory cytokines such as tumour necrosis factor α (TNFα) and interleukin (IL-6)." (PMID 37894480, 2023). "Daoy and UW228 cancer cells transduced with RGD4C.TPA.TNFα showed high level of TNFα mRNA expression, which was undetectable in cells treated with the mock targeted RGD4C.TPA lacking the TNFα transgene, or nontargeted TPA.TNFα vector lacking RGD4C." (PMID 37331004, 2023). "In the multivariate model while controlling for age, sex and other confounders, cancer risk in the SOT/HSCT and PID/SID cohort was significantly higher than the TNF-i cohort." (PMID 36624408, 2023). "Metastatic cancer cells can secrete many osteolytic factors, such as PTHrP, IL-6, TNF, etc., which stimulate OC proliferation and differentiation and produce osteolytic effects." (PMID 37746292, 2023). "It decreases the IL‐12 and tumor necrosis factor‐alpha (TNF‐∝), which jointly inhibit the angiogenesis of cancer cells and result in cancer cell death." (PMID 38455223, 2023). "Yet, the importance of CD4+ T cells in cancer elimination via secretion of effector cytokines such as interferon-γ (IFNγ) and tumor necrosis factor-α (TNFα) has also been reported." (PMID 39086686, 2023). "The discordant effects that TNFα can exert in cancer depend on a multitude of factors that include its concentration and the ratio of its two isoforms (mTNF, sTNF), among others." (PMID 36980727, 2023). "Many pro-inflammatory cytokines, such as IL-1, IL-6, and TNF- α, are involved in regulating the production of albumin in hepatocytes, and they also play a particular role in regulating angiogenesis and cancer progression." (PMID 37197434, 2023).
cancer (continued). "Our findings highlighted the potential of crude KL extracts and their compounds lupeol, citronellal and citronellol in stimulating M1 type polarization against cancer via TNF-α induced apoptosis." (PMID 36802384, 2023). "We evaluated the TNF-α expression in the treated animals to assess the efficacy of the formulation in treating induced cancer." (PMID 36903437, 2023). "In human cancer, Tumor Necrosis Factor can be found in stroma and malignant cells, lungs, breast, prostate, bladder, and colorectal cancer." (PMID 37298889, 2023). "Experimental studies on the effects of anesthetics/analgesics and perioperative care on TNF-α release and cancer cell biology." (PMID 36765695, 2023). "By engulfing cancer cells, secreting huge amounts of pro-inflammatory cytokines like IL-1, IL-12, and TNF-α, and luring T cells, M1 macrophages perform a pro-inflammatory function and take part in immune surveillance." (PMID 37563639, 2023). "Recently, a genome-wide siRNA screen identified that the regulation of TNF-α mRNA expression by transcription factor SP3 is a critical factor for SMs mediated cancer cell death." (PMID 36831656, 2023). "The existing evidence of the importance of TNFα in human cancers is therefore supplemented with the novel findings in the current study." (PMID 36980717, 2023). "For example, one study found increased serum levels of IL-6 and IL-7 (cancer-suppressive) in CD, and increased TNF-α, eotaxin and growth-related oncogene (a chemokine) in UC patients." (PMID 37681925, 2023). "Interest in the utility of TNF-α as a biomarker for early cancer detection connects with its discovered role in stepwise inflammation-mediated carcinogenesis." (PMID 36980727, 2023). "It has also been found that cancer cells are capable of directly synthesizing these factors, resulting in in vitro expression of TNF-α and IL-6 1000-fold higher in cancer cells compared to physiological ovarian epithelial cells." (PMID 37190027, 2023). "The findings exhibited that a few crucial cancer-related pathways, including TNF signaling pathway, cell cycle, HIF-1Alpha signaling pathway, IL-17 signaling pathway, and PI3K-Akt signaling pathway were considerably enhanced in the TFs’ downstream targets." (PMID 37589508, 2023). "Collectively, data suggested that inhibition of cancer cell growth was mediated by TNF-α produced by M1-type pro-inflammatory macrophages." (PMID 36802384, 2023). "There are data on the inhibition of the synthesis of TGFβ, TNFα, IL-6, and IL-1β by progestins in cancer cells." (PMID 37298830, 2023). "M1 macrophages can produce reactive oxygen species (ROS) and inflammatory cytokines, such as tumor necrosis factor-alpha (TNF-α) and interleukin-1 beta (IL-1β), which contribute to metabolic alterations and cancer-related inflammation." (PMID 37492564, 2023). "From these results, we concluded that the anti-OP IPRN is mainly involved in the PI3K-Akt signaling pathway, AGE-RAGE signaling pathway in diabetic complications, proteoglycans in cancer, TNF signaling pathway, and other biological pathways." (PMID 37069639, 2023). "TNFα-dependent radiation-induced cytotoxicity is attenuated by NFκB activity in many cancers, including HNSCC." (PMID 37055579, 2023). "The KEGG analysis indicated that DEIRGs were mainly enriched in cytokine–cytokine receptor interaction, TNF signaling pathway, and proteoglycans in cancer." (PMID 37373979, 2023). "For instance, tumor necrosis factor (TNF)-α and interleukin (IL)-1α can inhibit apoptosis, promoting the development of cancer cells." (PMID 37958564, 2023). "Our results showed that the functional modules involved in the positive regulation of tumor necrosis factor production or cellular response to cytokine stimulus were present in ten of the sixteen cancer types (red labels)." (PMID 37475016, 2023).
cancer (continued). "Each relapse AML sample showed over-representation of over- and under-expressed DEGs in TFs, drug-resistance genes, cancer-mutated genes (oncogenes and TSGs) and several cancer-related pathways (mTOR, MAPK, ErbB, FoxO, TNF and HIF-1 signaling, apoptosis)." (PMID 37031307, 2023). "During cancer immunostimulation, the secretion of TNF downregulates the expression of SLC7A11 and SLC3A2, and reduces the absorption of cysteine, leading to lipid peroxidation and iron deposition in cancer cells." (PMID 37681908, 2023). "The top 10 related KEGG signaling pathways consisted of pathways in cancer, relaxin signaling pathway, IL-17 signaling pathway, TNF signaling pathway, GC, cell cycle, microRNAs in cancer, etc." (PMID 37565919, 2023). "Inflammatory cytokines (interferons, TNF-α, IL-6, and IL-17) and inflammatory cells modulate the gene expression that regulates survival, proliferation, self-renewal, metastasis, and cancer stemness." (PMID 36979874, 2023). "It has also been reported that carnosine can increase the expression and secretion of the pro-inflammatory cytokine TNFα, which is known to induce cancer cell death." (PMID 37998326, 2023). "Similar to IL-12-based therapies, reducing therapeutic toxicities is vital for the future success of utilising TNFα in cancer treatment." (PMID 37455828, 2023). "They found that although the baseline plasma levels of IL-1 and TNF-α were elevated in cancer patients concerning healthy controls, plasma levels decreased postoperatively in all subjects and normalized within one week." (PMID 38067195, 2023). "Additional limitations include differences among studies in terms of cancer stage, concomitant treatments, length of follow up and time interval from diagnosis of cancer to TNF-antagonists use." (PMID 37113615, 2023). "KEGG analysis indicated that these co-expressed genes were closely related to the following pathways: pathways in cancer, tumor necrosis factor (TNF) signaling pathway, and sphingolipid signaling pathway." (PMID 37576398, 2023). "Some of the TNF-related lncRNAs included in our prognostic model have previously been reported to play an important role in cancer progression." (PMID 37153654, 2023). "They detected the statistically significant role of Il-8 and TNF-α and higher levels in malignant tumors." (PMID 37373969, 2023). "The opposite effect of P4 on cytokine production in cancerous and noncancerous cells has been demonstrated in studies: P4 mostly down-regulated IL-1β, IL-6, and TNFα in cancer cell lines and tissues." (PMID 37298830, 2023). "TNFα is a potent proinflammatory cytokine and promotes the development and progression of various cancers." (PMID 37208442, 2023). "In fact, the product label for anti TNF-α Ab warns against its application to patients with extant cancer." (PMID 37185713, 2023). "mRNA‐seq showed that differentially expressed transcripts between vector and shN cells were enriched in pathways related to protein processing in the endoplasmic reticulum, microRNA in cancer, cell cycle and TNF signalling pathway." (PMID 37983928, 2023). "As chronic inflammation is a key risk factor for developing various malignancies, inflammatory mediators, including IL-6 and TNFα are known to be involved in carcinogenesis and cancer progression." (PMID 37628724, 2023). "Elevated levels of IL-1β, IL-6, and TNF-α impair systemic insulin sensitivity and promote cancer development." (PMID 37175211, 2023). "In line with our findings, a previous study reported that TNF-α stimulates nuclear translocation of p65 in human cancer cells." (PMID 38067111, 2023). "TNF-alpha acting by TNFR1 receptors inhibits cancer development while activating TNFR2 promotes cancer development." (PMID 37753372, 2023). "In cancer development, mast cells can promote tumorigenesis and invasion by releasing pro-inflammatory and angiogenic mediators such as TNFα, IL-6, VEGFs, and matrix-degrading enzymes." (PMID 37445862, 2023).